CCDC186 (coiled-coil domain containing 186)
Synonyms: C10orf118; FLJ10188; FLJ35301; CCCP-1; golgin104; CCCP1
Tractability: PROTAC: ubiquitination databases record sites on it; its protein half-life has been measured.
Gene: Protein-coding gene on chromosome 10 (114,120,862 to 114,174,232, reverse strand). Ensembl gene ENSG00000165813.
Subcellular location (Human Protein Atlas): Golgi apparatus
Gene Ontology:
Molecular function: small GTPase binding
Biological process: vesicle cytoskeletal trafficking
Cellular component: trans-Golgi network; Golgi apparatus
Genetic constraint (gnomAD): Loss-of-function variants: 42 observed, 96.94 expected, observed/expected ratio (o/e) 0.43, 90% interval 0.34 to 0.56. The upper end of that interval is the gene's LOEUF score, 0.56, which puts it in group 2 of 6, group 1 being the genes least tolerant of losing a copy. Missense variants: 808 observed, 949.37 expected, observed/expected ratio (o/e) 0.85, 90% interval 0.8 to 0.9. Synonymous variants: 326 observed, 332.94 expected, observed/expected ratio (o/e) 0.98, 90% interval 0.89 to 1.07.
Homologues: Orthologues: chimpanzee CCDC186 (99% identical), macaque CCDC186 (95% identical), dog CCDC186 (92% identical), pig CCDC186 (91% identical), rabbit CCDC186 (90% identical), mouse Ccdc186 (84% identical), rat Ccdc186 (84% identical), guinea pig CCDC186 (76% identical), tropical clawed frog ccdc186 (64% identical), zebrafish ccdc186 (62% identical), Drosophila melanogaster Golgin104 (24% identical), Caenorhabditis elegans cccp-1 (21% identical).
Diseases named in the same sentence as CCDC186 in open-access papers:
CCDC186 is named in the same sentence as 21 diseases in open-access papers, as found by Europe PMC text mining. Sharing a sentence is not in itself a finding about the gene and the disease. The quoted sentences say what the papers report.
Brain atrophy (2 papers, 2021 to 2023). Partial or complete wasting (loss) of brain tissue that was once present. "To date, variants in CCDC186 have only been reported in two unrelated individuals presenting with failure to thrive, visual impairment, neurodevelopmental delay, hypotonia, and brain atrophy." (PMID 37569695, 2023).
developmental delay (2 papers, 2021). "We report a second pediatric patient with a CCDC186‐associated phenotype comprising of failure to thrive, developmental delay and medically refractory epilepsy, providing further evidence for a disease association of CCDC186 variants." (PMID 33259146, 2021). "However because patient ID5 only has a heterozygous DMXL2 variant, the developmental delay may also be due to other causes, such as variants in CCDC186 (MIM 619249; 10q25.3), ZRF2 or MCM3AP (MIM 603294; 21q22.3)." (PMID 33924653, 2021).
Failure to thrive (2 papers, 2021 to 2023). Failure to thrive (FTT) refers to a child whose physical growth is substantially below the norm. "In the affected individuals, truncating CCDC186 variants additionally lead to severe failure to thrive." (PMID 33259146, 2021). "To date, CCDC186 disease-associated variants have only been reported in one patient within a large sequencing study of 1000 cases from Saudi Arabia and in a single patient presenting developmental delay, refractory epilepsy, and failure to thrive." (PMID 37569695, 2023).
Hypoglycemia (2 papers, 2021 to 2023). A decreased concentration of glucose in the blood. "This hypothesis agrees with previous studies showing that CCDC186 knock-out mice result in postnatal lethality, aberrant glucose homeostasis, and defective hormone secretion that leads them to hypoglycemia." (PMID 37569695, 2023). "While cccp‐1 knockout in C. elegans results in a neurologic phenotype of impaired and slowed locomotion, homozygous Otg1/CCDC186 knockout mice show severe postnatal growth retardation and preweaning lethality as well as impaired glucose metabolism with hypoglycemia and low levels of serum insulin." (PMID 33259146, 2021).
Epileptic encephalopathy (1 paper, 2021). A condition in which epileptiform abnormalities are believed to contribute to the progressive disturbance in cerebral function. "Taken together, our findings confirm the association of biallelic loss‐of‐function in CCDC186 with a phenotype including epileptic encephalopathy and growth retardation." (PMID 33259146, 2021).
insulinoma (1 paper, 2021). "The critical role of CCDC186 in cargo sorting and insulin secretion upon stimulation was recently confirmed in rat insulinoma cells." (PMID 33259146, 2021).
neurodevelopmental disorder (2 papers, 2021 to 2023). A behavioral and cognitive disorder with onset during the developmental period that involves impaired or aberrant development of intellectual, motor, or social functions. "Mutations in genes involved in DCV regulation, other than CCDC186, have been described in patients with neurodevelopmental disorders." (PMID 37569695, 2023). "To date, an association of biallelic loss‐of‐function variants in CCDC186 with a neurodevelopmental disorder has been proposed and described in a single patient." (PMID 33259146, 2021). "Exome sequencing identified a homozygous loss‐of‐function variant in CCDC186 (NM_018017.2) c.767C> G; p.(Ser256Ter) thus providing further evidence to support CCDC186 as a new disease gene for an autosomal recessive neurodevelopmental disorder." (PMID 33259146, 2021).
CCDC186 also shares sentences with these, for which no sentence is quoted: cancer (3 papers); breast carcinoma (2); tumor (2); breast tumour (1); chronic pancreatitis (1); cutaneous T-cell lymphoma (1); fungal infection (1); infection (1); infiltrating ductal carcinoma (1); Micropenis (1); Nervous (1); Pleural effusion (1); renal cell carcinoma (1); testis (1).